MCAM (melanoma cell adhesion molecule)
Diseases named in the same sentence as MCAM in open-access papers (continued):
Sharing a sentence is not in itself a finding about the gene and the disease.
melanoma (continued). "Another important mechanism for metastasis is the cooperation between PAR-1 and PAFR to regulate the expression of MCAM/MUC18 (melanoma cellular adhesion molecules)." (PMID 35603177, 2022). "The crosstalk between protease-activated receptor 1 and platelet-activating factor receptor has been demonstrated to regulate the expression of melanoma cell adhesion molecule (MCAM/MUC18) metastasis of melanoma." (PMID 36185647, 2022). "Overall, galectin-3 is identified in this study as a natural ligand of the MCAM in melanoma cells, and their interaction induces MCAM clustering and subsequent AKT activation." (PMID 36291660, 2022). "MCAM has been reported to be recognized by galectin-1 in melanoma cells, and their interaction increased melanoma cell migration." (PMID 36291660, 2022). "Although the activation of AKT signalling is believed to be critical in MCAM-mediated melanoma progression, several other singling pathways have been reported to also occur following MCAM activation." (PMID 36291660, 2022). "As MCAM dimerization is known to occur in the activation of MCAM in melanoma, we then investigate the influence of exogenous introduction of galectin-3 on MCAM dimerization." (PMID 36291660, 2022). "MCAM-mediated melanoma progression is believed to be initiated through MCAM dimerization on cell surface, with subsequent induction of downstream AKT signalling, a feature that occurs at various stages of melanoma progression." (PMID 36291660, 2022). "Intraperitoneal application of anti-MCAM antibody significantly inhibited melanoma growth and metastasis, whereas the depletion of MCAM completely abolished melanoma metastasis in mice." (PMID 36291660, 2022). "Previous studies showed that CD146 is not only a melanoma cell adhesion molecule but also a cellular surface receptor of various ligands, participating in numerous physiological and pathological processes." (PMID 34461987, 2021). "Recently, it was shown that CD146/MCAM (melanoma cell adhesion molecule) is essential for melanoma cell adhesion and metastasis." (PMID 33969605, 2021). "Melanoma cells themselves can express melanocyte adhesion molecule (MCAM)/MUC18, L1-CAM, α4β1-integrin and αvβ3-integrin that promote transendothelial migration." (PMID 33870460, 2021). "Recently, we showed that MCAM/MUC18/CD146 and ABCB5 can serve as melanoma-specific-targets in the selection of highly primitive circulating melanoma cells, and constitute putative proteins associated with disease spreading progression." (PMID 34830300, 2021). "Yazawa confirmed this with results showing that melanoma cell adhesion molecule (MCAM) was one of the major melanoma cell Gal-1 ligands and was largely dependent on its N-glycans for Gal-1-binding." (PMID 34680031, 2021). "Mechanistically, GCNT3 led to increased S100A8/A9-mediated cell migration and invasion through the stabilization and activation of melanoma cell adhesion molecule (MCAM)." (PMID 34440905, 2021). "Several members of the IgSF, including MCAM (CD146), NCAM (CD56), ALCAM (CD166), and L1-CAM (CD171) have been associated with metastasis in several cancers such as melanoma." (PMID 34207884, 2021). "In melanoma, metastasis is promoted by Gal-3 interaction with MCAM, leading to cytokine secretion from vascular endothelial cells." (PMID 34112916, 2021). "In particular, in our previous study, in B16F10 melanoma cells, MCAM expression was reduced to a similar degree at mRNA and protein levels: 82% at the mRNA level and 69% at the protein level." (PMID 32204304, 2020). "CMCs are phenotypically and molecularly heterogeneous, thus we performed a “home-made Liquid-Biopsy,” by targeting the melanoma-associated-antigen, MCAM/MUC18/CD146, and/or the melanoma-initiating marker, ABCB5." (PMID 32548126, 2020). "In this study, we demonstrated that MCAM silencing with GET effectively radiosensitizes tumors, both melanoma tumors that highly express MCAM and carcinoma tumors with a low expression of MCAM." (PMID 32204304, 2020).
melanoma (continued). "In other studies, silencing MCAM with siRNA or plasmid DNA-encoding shRNA against MCAM reduced the proliferation in HUVEC for 40% in B16F1 melanoma cells for 79% and in B16F10 melanoma for 65%." (PMID 32204304, 2020). "This study indicates a radiosensitization of two radioresistant tumor models, B16F10 melanoma and TS/A carcinoma, expressing high and low levels of MCAM, after silencing MCAM using the GET of pMCAM that was more pronounced in melanoma than in carcinoma." (PMID 32204304, 2020). "S100A8/A9/RAGE, S100A8/A9-ALCAM, and S100A8/A9/MCAM axes mediate malignant melanoma progression through the activity of nuclear factor kappa beta (NF-κB) and production of reactive oxygen species (ROS)." (PMID 33256110, 2020). "The result of the current study indicates the more pronounced response of melanoma to radiosensitization by silencing MCAM after GET than carcinoma, as significantly higher immune cell infiltration and resistance to the secondary challenge were determined." (PMID 32204304, 2020). "SSSRs encompass Extracellular Matrix Metalloproteinase Inducer (EMMPRIN), Activated Leukocyte Cell Adhesion Molecule (ALCAM), Toll-like Receptor 4 (TLR-4), Neuroplastin (NPTN) β, and Melanoma Cells Adhesion Molecule (MCAM)." (PMID 33256110, 2020). "Herein, we described how CMC subpopulations expressing MCAM, as melanoma-associated antigen and/or ABCB5, as melanoma-initiating marker, display distinct gene profiles." (PMID 32548126, 2020). "MUC18 also called melanoma cell adhesion molecule (MCAM) or CD146, is a glycoprotein that is associated with gallbladder cancer and melanoma and that is also detected in pancreatic cancer stroma." (PMID 33182511, 2020). "In vivo, intratumoral treatment with antibodies against MCAM in melanoma, hepatocarcinoma, osteosarcoma, leiomyosarcoma, and pancreatic tumors reduced tumor growth and the formation of metastases in melanoma and osteosarcoma." (PMID 32204304, 2020). "The GFP+ cells in the dermis were found to downregulate E-cadherin expression and upregulate MCAM expression, which is consistent with our and previous observations of human melanoma at the invasive radial growth phase 49,50." (PMID 31685822, 2019). "Comparison of melanoma cell capture using anti-MCAM (clone P1H12), anti-MCSP (clone 9.2.27) revealed cells expressing both proteins (SKMel28) were isolated with either antibody." (PMID 30735560, 2019). "Using enriched normal mouse melanocytes and cancerous B16-BL6 cells, we compared the expression levels of melanoma cell adhesion molecule (MCAM), an important membrane protein for melanoma metastasis, in the cells." (PMID 30899801, 2019). "Tyrosinase is involved in the synthesis of melanin, MAGE-3 is involved in malignant transformation and is the main tumour-specific melanoma antigen, and MCAM is involved in cell adhesion." (PMID 31572192, 2019). "Targeting MCAM alone has previously shown to satisfactorily recover SkMel-28 melanoma cells (74–88% recovery) spiked into blood with the CellSearch isolation platform." (PMID 30735560, 2019). "Our data confirms heterogeneous levels of MCAM expression in 6 melanoma cell lines, which is in keeping with MCAM expression in tissue of 68% of primary melanoma and 89% of melanoma lymph node metastases." (PMID 30735560, 2019). "We confirmed that the expression level of MCAM was highly elevated in various human melanoma cell lines in a consistent manner when compared to that of normal human melanocytes from a commercial source (our unpublished data)." (PMID 30899801, 2019). "When the isolated melanocytes were eventually compared with B16-BL6 melanoma cells for their intrinsic MCAM expression, we confirmed that MCAM shows markedly higher expression at the protein level in B16-BL6 melanoma cells than in normal mouse melanocytes." (PMID 30899801, 2019).
melanoma (continued). "Wnt5a signaling results in acyl protein thioesterase 1 (APT1) mediated depalmitoylation of pro-metastatic cell adhesion molecules CD44 and MCAM, resulting in increased melanoma invasion." (PMID 29648538, 2018). "Melanoma supernatants indicate the presence of exosomes containing melanoma antigen recognized by T cells 1 (Mart-1) and melanoma cell adhesion molecule (Mel-CAM)." (PMID 30108680, 2018). "Analysis of MCAM expression in human melanoma tissue microarrays (TMAs) revealed that MCAM was more frequently expressed in metastases as compared to primary melanomas (p = 0.0001) in agreement with previous findings." (PMID 29491397, 2018). "MCAM/CD146 (melanoma cell adhesion molecule) was originally identified as a marker of melanoma progression." (PMID 28636767, 2017). "Both MSN and MCAM are highly expressed in metastatic melanoma cells and known to regulate cell migration." (PMID 28923978, 2017). "CD146 was originally identified in 1987 as a tumor marker for melanoma and is also known as Melanoma Cell Adhesion Molecule (MCAM or Mel-CAM)." (PMID 28245592, 2017). "We showed that MCAM/MUC18/CD146 RT-PCR assay for CMCs correlated with melanoma diagnosis and progression of the disease." (PMID 28280601, 2017). "Whole protein was isolated following cell aggregation assays.Melanoma cell adhesion molecule (MCAM) correlated with NHE1 expression in thatNHE1-overexpressing cells showed a 90% higher amount compared to control." (PMID 28205573, 2017). "CD146, also known as melanoma cell adhesion molecule, was initially identified as a marker of melanoma progression and metastasis." (PMID 28652617, 2017). "Negative regulation of stromal formation was observed to occur by CD146—also known as melanoma-specific cell adhesion molecule (MCAM)—signaling." (PMID 28351381, 2017). "PAR-1 also promotes expression of melanoma cell adhesion molecule MCAM/MUC18 (MUC18), a crucial marker of melanoma metastasis." (PMID 28752248, 2017). "MCAM protein is frequently overexpressed on the surface of advanced and metastatic human melanoma cells; however, its expression is rare in benign nevi." (PMID 27029003, 2016). "MCAM encodes the melanoma cell adhesion molecule; increased expression of MCAM in human melanoma cells leads to increased tumor growth and metastasis." (PMID 27467526, 2016). "Among them we found MGAT5, which in melanoma plays a role during the transition from the vertical growth phase to the metastatic stage, together with its targets MCAM, and TGFβ expressed in most malignant melanomas and correlating with poor survival." (PMID 26912358, 2016). "Our observation was in line with a previous study on melanoma in which miR-573 exerted its oncosuppressor activity by targeting the melanoma cell adhesion molecule (MCAM)." (PMID 25333258, 2015). "MCAM has classically been described in melanoma cells but it also seems to play a role in hepatocellular carcinoma via its interplay with ALCAM which can itself be ubiquitinated (see also Section 4.4)." (PMID 26703751, 2015). "Our study shows that MCAM/MUC18 RT-PCR assay for CMCs correlates well with melanoma diagnosis and progression of the disease." (PMID 24902661, 2014). "Many reports indicate that MCAM/MUC18 correlates with tumour thickness and metastatic potential of human melanoma cells in mice." (PMID 24902661, 2014). "Our present investigations evidence a correspondence among MCAM/MUC18 mRNA blood level, detection and degree of expression of this marker on the corresponding primary melanoma tissue, tumour thickness, AJCC stages and clinical outcome." (PMID 24902661, 2014). "Semiquantitative immunohistochemical MCAM/MUC18 staining on corresponding primary melanomas was related to peripheral molecular expression." (PMID 24902661, 2014). "CTCs were captured by targeting the melanoma associated markers MCSP and MCAM as well as the melanoma stem cell markers ABCB5 and CD271." (PMID 24915896, 2014).
melanoma (continued). "The results of this study demonstrate that MCAM is a valuable therapeutic target in melanoma tumors, the level of which can be effectively reduced at mRNA and protein levels by a plasmid DNA encoding shRNA against MCAM." (PMID 25350580, 2014). "This would be consistent with the proposal that MCAM/MUC18 is thought to play a role in cell–cell and cell–matrix interactions, being the surgical manipulation a possible cause of shedding of melanoma cells into circulation." (PMID 24902661, 2014). "Effectively, molecular MCAM/MUC18 negativity documented in the six poor outcome melanoma patients out of the 14 AJCC III–IV stages was correlated with absence or low level of MCAM/MUC18 antigen staining." (PMID 24902661, 2014). "Using this assay, we evaluated the co-expression of five MAMs, Tyr-OH, MART-1, MAGE-3, p97 and MCAM/MUC18, in melanoma patients stratified according to early and advanced stages of the disease." (PMID 24902661, 2014). "These two studies made use of the CellSearch Melanoma Kit which captures melanoma cell adhesion molecule (MCAM)-expressing cells and detects melanoma chondroitin sulfate proteoglycan (MCSP)-positive cells as CTCs." (PMID 24915896, 2014). "The constructed pMCAM was tested for its effectiveness in the reduction of MCAM mRNA and protein levels in melanoma and endothelial cells." (PMID 25350580, 2014). "The melanoma cell adhesion molecule (MCAM) is a multi-functional transmembrane glycoprotein that has an important role in the development of melanoma as well as its progression, including invasiveness, metastatic potential and vascular angiogenesis." (PMID 25350580, 2014). "The melanoma cell adhesion molecule (MCAM) is involved in melanoma development and its progression, including invasiveness, metastatic potential and angiogenesis." (PMID 25350580, 2014). "SIN DNA vectors have been employed for the expression of the murine melanoma cell adhesion molecule (MCAM/MUC18) as a vaccine against murine melanoma, which resulted in the induction of humoral and CD8+ T-cell immune responses against melanoma." (PMID 24937089, 2014). "Amongst them, CD146, also known as MCAM or Muc18, is a member of the immunoglobulin superfamily, which was originally identified as a marker for malignant melanoma." (PMID 24756564, 2014). "Immunohistochemical investigation revealed a constant and mainly cytoplasmatic positivity for MCAM/MUC18 antigen in melanoma cells." (PMID 24902661, 2014). "If advanced and metastatic melanomas (80 %) strongly express MCAM/MUC18, the detection of this antigen on thin melanoma or benign melanocytic nevus is weaker and less frequent." (PMID 24902661, 2014). "In melanoma, MCAM appears to facilitate cell migration by the rearrangement of the cellular cytoskeleton via activation of Rho proteins, and potentially via activation of the AKT and P38 MAPK pathway in association with VEGRF." (PMID 24069584, 2013). "MCAM, CSPG4, and Gal-3 are associated with angiogenesis and CSPG4 is involved with the activation of pro-MMP-2 on melanoma (relevant references are in the review)." (PMID 24069584, 2013). "This review has focused on five molecules involved in melanoma metastasis – MCAM, Gal-3, CSPG4, MMP-2, and PAX-3." (PMID 24069584, 2013). "Melanoma cell adhesion molecule (MCAM/MUC18/CD146) is known to be a tumor progression marker of human melanoma that plays a role in cell adhesion." (PMID 24058910, 2013). "There is also evidence that MCAM expression in melanoma cells modulates the expression and/or activity of integrin chains." (PMID 24069584, 2013). "MCAM is expressed on approximately 70% of primary melanoma and 90% of lymph node metastases, and MCAM expression in a primary lesion is predictive of lymph node metastases and metastases at other sites." (PMID 24069584, 2013). "Although a homophilic interaction between MCAM cannot be demonstrated, it is possible that melanoma and endothelial cells both express MCAM and its ligand, and these interact bi-directionally." (PMID 24069584, 2013).
melanoma (continued). "CD146 was originally identified as a marker for melanoma (MCAM), due to its overexpression in metastatic lesions and advanced primary tumors, yet not in benign lesions." (PMID 23599761, 2013). "Both rounded and elongated HT-1080s and WM239a cells formed similar uropod-like structures that were enriched with melanoma cell adhesion molecule (MCAM/cd146/MUC18), β1-integrin, and F-actin." (PMID 24349113, 2013). "On melanoma cells, MCAM mediates cation independent cell–cell adhesion, moderates cell-matrix interactions and is associated with increased cell migration and invasion, as seen in in vitro scratch wound and invasion assays." (PMID 24069584, 2013). "MCAM exists as monomers and dimers on the surface of both endothelial and melanoma cells; with dimerization mediated through a disulfide bond occurring between cysteine residues in the most membrane proximal Ig domain." (PMID 24069584, 2013). "For example, the overexpression of MCAM in melanoma cells can promote the growth and metastasis of xenograft tumours in nude mice." (PMID 22610942, 2012). "Previous studies have found that MCAM over-expression can promote tumourgenesis and growth of melanoma cells in nude mice." (PMID 22610942, 2012). "MCAM expression by melanoma cells has also been shown to activate NF-κB via the upstream p38 mitogen-activated protein kinase (MAPK)." (PMID 22272201, 2012). "A member of the immunoglobulin superfamily, melanoma cell adhesion molecule (MCAM; also known as CD146 or MUC18) was first identified in melanoma." (PMID 22610942, 2012). "Earlier studies have shown that the overexpression of MCAM in melanoma increased the expression of matrix metalloproteinase-2 (MMP-2), thereby contributing to the degradation of the extracellular matrix by tumour cells and promoting metastasis." (PMID 22610942, 2012). "MCAM expression has been well studied in melanoma, and MCAM expression on tumor cells appears to confer metastatic potential onto non-metastatic cells." (PMID 22792325, 2012). "For example, in melanoma, elevated MMP-2 expression has been associated with increased levels of MCAM and NCAM." (PMID 22272201, 2012). "MCAM was initially considered to be the characteristic antigen that distinguishes malignant melanoma from benign or borderline melanoma." (PMID 22610942, 2012). "Melanoma cell adhesion molecule/CD146, Platelet Endothelial Cell Adhesion Molecule-1/CD31, ICAM-1, and ICAM-2 are adhesion proteins participating in the recruitment of leukocytes to sites of tissue injury and inflammation." (PMID 21245959, 2011). "Compared to naevi, primary melanomas showed MCAM expression in a larger proportion of PAX3-positive cells, 56.4%, which are again primarily located in the dermal component of the lesion." (PMID 20421967, 2010). "Samples of melanoma metastases showed MCAM expression in the majority (93.2%) of PAX3-positive cells." (PMID 20421967, 2010). "Since AP-2α regulates several genes associated with the metastatic potential of melanoma including c-KIT, VEGF, PAR-1, MCAM/MUC18, and p21Waf1, our data identified CREB as a major regulator of the malignant melanoma phenotype." (PMID 20805990, 2010). "Our results confirm co-expression of PAX3 and MCAM in melanomas and naevi, mainly in the cells that form nests located in the dermal component of the lesion, with melanoma samples showing larger numbers of PAX3, MCAM-positive cells compared to naevi." (PMID 20421967, 2010). "We have previously shown that the level of expression of MCAM/MUC18 in melanoma directly correlates with tumor progression and the acquisition of metastatic potential as it is transcriptionaly regulated by both AP-2α and CREB." (PMID 20805990, 2010). "Even though MCAM is frequently expressed in naevi its increased expression in melanomas shows significant correlation with poor disease free survival and mortality." (PMID 20421967, 2010).